MIB2 (MIB E3 ubiquitin protein ligase 2)
Description:
E3 ubiquitin-protein ligase that mediates ubiquitination of Delta receptors, which act as ligands of Notch proteins. Positively regulates the Delta-mediated Notch signaling by ubiquitinating the intracellular domain of Delta, leading to endocytosis of Delta receptors.
Synonyms: ZZANK1; skeletrophin; ZZZ5; FLJ39787
Tractability: Antibody: its Gene Ontology location is reachable by antibodies, with medium confidence. PROTAC: UniProt records ubiquitination sites on it; ubiquitination databases record sites on it; its protein half-life has been measured.
Gene: Protein-coding gene on chromosome 1 (1,615,434 to 1,630,610, forward strand). Ensembl gene ENSG00000197530.
Subcellular location: Cytoplasm; Endosome
Pathways (Reactome):
Signal Transduction: Activated NOTCH1 Transmits Signal to the Nucleus; NOTCH2 Activation and Transmission of Signal to the Nucleus; NOTCH3 Activation and Transmission of Signal to the Nucleus; Regulation of TNFR1 signaling; TNFR1-induced proapoptotic signaling
Disease: Constitutive Signaling by NOTCH1 HD Domain Mutants; Constitutive Signaling by NOTCH1 HD+PEST Domain Mutants; Constitutive Signaling by NOTCH1 PEST Domain Mutants
Immune System: Antigen processing: Ubiquitination & Proteasome degradation; PD-L1(CD274) glycosylation and translocation to plasma membrane
Gene Ontology:
Molecular function: protein binding; ubiquitin-protein transferase activity; ubiquitin protein ligase activity; metal ion binding; zinc ion binding
Biological process: positive regulation of canonical NF-kappaB signal transduction; protein ubiquitination; regulation of tumor necrosis factor-mediated signaling pathway
Cellular component: cytoplasm; cytosol; Golgi membrane; early endosome; endosome; plasma membrane; ubiquitin ligase complex
Genetic constraint (gnomAD): Loss-of-function variants: 78 observed, 77.77 expected, observed/expected ratio (o/e) 1, 90% interval 0.83 to 1.21. The synonymous counts are far from expectation, so gnomAD's model fits this gene poorly and the ratio says little. Missense variants: 1,543 observed, 1,249.7 expected, observed/expected ratio (o/e) 1.23, 90% interval 1.18 to 1.29. Synonymous variants: 820 observed, 567.42 expected, observed/expected ratio (o/e) 1.45, 90% interval 1.36 to 1.53.
Homologues: Orthologues: macaque MIB2 (98% identical), pig MIB2 (93% identical), rat Mib2 (92% identical), mouse Mib2 (89% identical), chimpanzee MIB2 (89% identical), guinea pig MIB2 (80% identical), dog MIB2 (73% identical), tropical clawed frog mib2 (67% identical), zebrafish mib2 (51% identical), Drosophila melanogaster mib2 (44% identical), Caenorhabditis elegans mib-1 (19% identical). Paralogues in human: MIB1 (41% identical).
Diseases named in the same sentence as MIB2 in open-access papers:
MIB2 is named in the same sentence as 44 diseases in open-access papers, as found by Europe PMC text mining. Sharing a sentence is not in itself a finding about the gene and the disease. The quoted sentences say what the papers report.
melanoma (5 papers, 2018 to 2025). A malignant, usually aggressive tumor composed of atypical, neoplastic melanocytes. "When testing the effect of endothelial MIB2 deficiency on B16 melanoma tumor growth, we observed a significantly increased tumor volume after subcutaneous injection of tumor cells in EC-Mib2-KO mice." (PMID 37031213, 2023). "Deleterious mutations in the MIB2 gene are associated with melanoma invasion, and could explain the occurrence of melanoma in the proband." (PMID 30233642, 2018). "LOH or promoter hypermethylation of MIB2 has been associated with melanoma invasion." (PMID 30233642, 2018). "This is in agreement with previously published data, showing that IM upregulates CXCL8 in keratinocytes, fibroblast, neutrophils and melanoma cells in vitro as well as MIB-2, the murine homologue of CXCL8, in IM-treated mouse skin." (PMID 30266096, 2018). "MIB2 is an E3 ligase, which has recently been shown to mediate ubiquitination of PD-L1 in murine melanoma B16 cells and colorectal carcinoma MC38 cells, and to thereby facilitate the transport of PD-L1 from the trans-Golgi network to the plasma membrane to prevent T-cell-mediated tumor cells death." (PMID 40478800, 2025).
glioma (3 papers, 2019 to 2023). A benign or malignant brain and spinal cord tumor that arises from glial cells (astrocytes, oligodendrocytes, ependymal cells). "Upregulation of E3 ligase skeletrophin (Mind bomb-2, MIB2) in glioma cells and clinical samples induces resistance to apoptosis via ubiquitination-mediated protection of NF-κB." (PMID 32984016, 2020). "In addition, it is intriguing that MIB2 is also reported to regulate cell apoptosis through B cells in glioma." (PMID 37436668, 2023). "MIB1 also plays a role in angiogenesis and MIB2 may be a positive regulator of NF-kB signaling, both of which are important in glioma pathogenesis." (PMID 31475119, 2019). "While KRT24, itself, has not been studied in the context of glioma, it has been experimentally determined to be associated with MIB1 and MIB2, which are involved in Notch signaling pathway in brain tumors." (PMID 31475119, 2019).
viral infection (3 papers, 2012 to 2018). "Most TBK1 activity was restored 12 hr after viral infection in mib1−/− and MIB1/MIB2 double deficient MEFs." (PMID 23028469, 2012).
lung cancer (2 papers, 2023). A malignant neoplasm involving the lung. "Using the public GEO dataset (GSE 30,219 and GSE75037), we observed that MIB2 expression was up regulated in lung cancer tissue and was associated with advanced stages and worse prognosis of lung cancer patients." (PMID 37436668, 2023). "In our research, we demonstrate that MIB2 is highly expressed in lung cancer cell lines and is associated with metastasis, staging, and survival time of non-small cell lung cancer." (PMID 37436668, 2023). "MIB2 promotes the proliferation, migration, and invasion of lung cancer cell lines by regulating cyclins, CDKs and EMT-related proteins." (PMID 37436668, 2023). "To investigate the clinical relevance of our findings, we collected 93 non–small cell lung cancer (NSCLC) specimens for IHC analysis of MIB2 and PD-L1." (PMID 36719382, 2023). "Knockdown of MIB2 significantly attenuates the metastatic and invasive ability of A549 and H1299 lung cancer cell lines." (PMID 37436668, 2023). "MIB2 is up regulated in lung cancer tissue compared to adjacent normal lung tissue according to both public databases and our clinical lung cancer samples." (PMID 37436668, 2023). "We explored the expression of MIB2 in lung cancer samples and normal lung tissue in public databases including GEO and TCGA database, which was a strong evidence that MIB2 promoted the development of lung cancer." (PMID 37436668, 2023). "Collectively, MIB2 is significantly up regulated in lung cancer tissue and is positively correlated with poor prognosis of non-small cell lung cancer patients." (PMID 37436668, 2023). "Then, we performed the transwell and wound healing assay to study the role of MIB2 on the metastasis and invasion of lung cancer." (PMID 37436668, 2023). "After conducting CCK8 assay, we found that MIB2 knockdown inhibited lung cancer cell proliferation, while overexpression of MIB2 can save the decrease of cell proliferation caused by MIB2 knockdown." (PMID 37436668, 2023). "To further examine the role of MIB2 in lung cancer, we detected MIB2 expression in 8 pairs of clinical samples through immunoblotting technique and found that MIB2 expression in lung cancer tissue was also up regulated compared with the adjacent normal tissue." (PMID 37436668, 2023). "We confirmed the promoting role of MIB2 in the occurrence and proliferation of lung cancer through proliferation and cloning experiments." (PMID 37436668, 2023). "It is worth noting that MIB2 is reported to be a suppressor in lung cancer, which discover that MIB2 inhibits the proliferation, migration, and invasion of non-small cell lung cancer through ubiquitination of Notch1." (PMID 37436668, 2023). "Proteins of cell cycle control pathways are detected to verify the potential mechanism of MIB2 in lung cancer progression." (PMID 37436668, 2023). "We suggest that MIB2 indirectly regulate the proliferation of lung cancer cells by regulating these cell cycle-related proteins." (PMID 37436668, 2023). "Nevertheless, few studies have been performed on the biological effects and molecular functions of MIB2 in lung cancer development." (PMID 37436668, 2023). "We carried out CCK8 and clone assays to study the influence of MIB2 in lung cancer proliferation." (PMID 37436668, 2023). "We analyzed the expression of MIB2 in lung cancer samples by performing Rt-PCR and western blot." (PMID 37436668, 2023). "Knockdown of MIB2 can significantly promote the apoptosis of lung cancer cells, which indicates that MIB2 may play a role in the occurrence and development of lung cancer by inhibiting apoptosis." (PMID 37436668, 2023). "Knockdown of MIB2 inhibits proliferation, metastasis, and invasion of lung cancer cell lines." (PMID 37436668, 2023). "Besides, we detected the MIB2 expression in 65 pairs of lung cancer using Real-time PCR and found that MIB2 was significantly up regulated in lung cancer tissue compared with the adjacent normal lung tissue (P = 0.0007)." (PMID 37436668, 2023).
lung cancer (continued). "MIB2 positively correlates with membrane PD-L1 levels in non–small cell lung cancer." (PMID 36719382, 2023). "More importantly, we provide the evidence that MIB2 is involved in modulating the cell cycle which may be the mechanism related to lung cancer proliferation." (PMID 37436668, 2023). "In our study, we are dedicated to discovering the role of MIB2 in lung cancer development." (PMID 37436668, 2023). "Clone assays also showed that MIB2 knockdown inhibited lung cancer clone ability, while MIB2 overexpression could rescue the inhibition of lung cancer proliferation." (PMID 37436668, 2023). "The accordant variations between MIB2 and cyclins confirm the promoting role of MIB2 in lung cancer cells and remind us that MIB2 may activate the progression of lung cancer through promoting the accumulation of cell cycle complexes." (PMID 37436668, 2023). "Collectively, our study revealed that MIB2 promoted the occurrence of lung cancer by regulating cell cycle, which may help to promote the development of new diagnostic or therapeutic biomarker to improve the prognosis of patients with NSCLC." (PMID 37436668, 2023). "Besides, MIB2 is also negatively correlated with lung cancer prognosis." (PMID 37436668, 2023). "Based on these results, we detected MIB2 expression in NSCLC cell lines and clinical lung cancer tissue collected by ourselves." (PMID 37436668, 2023). "By analyzing the GEO datasets (GSE 75,037 & 30,219), we finally focused on MIB2 (Mind Boom 2), an E3 ubiquitin protein, was highly expressed in lung cancer samples compared to non-cancer tissue." (PMID 37436668, 2023).
Autoimmunity (1 paper, 2019). The occurrence of an immune reaction against the organism's own cells or tissues. "Similarly pertinent, because of their involvement in autoimmunity, are AKNA and MIB2 genes." (PMID 31511551, 2019).
bladder cancer (1 paper, 2023). "Two E3 ligases were identified, E3 ubiquitin-protein ligase (MIB2) and E3 ubiquitin protein ligase NEDD4 like (NEDD4L), that were significantly downregulated in the separated sEVs of patients with a first diagnosis of bladder cancer." (PMID 37371512, 2023).
breast carcinoma (1 paper, 2021). "Among the candidate CpGDMs, we found eight genes with differential methylation previously associated with breast cancer susceptibility and pathology in the G2SBC and COSMIC Databases (AMOTL1, CDCP1, CYFIP1, MAP3K6, MIB2, SDK1, TAL1, and TYROBP)." (PMID 33145876, 2021). "Hypermethylation of CYFIP1 gene (only CpGDM hypermethylated in patients) was observed in patients with breast cancer (P = 2.22 × 10−12), while MAP3K6 and MIB2 gene promoters showed a slight hypomethylation in BCP." (PMID 33145876, 2021).
cerebral artery occlusion (1 paper, 2020). "Similarly, in the animal model of transient middle cerebral artery occlusion (tMCAo), Mib2 levels were significantly increased after 3 h and 9 h of reperfusion, suggesting that Mib2 might be involved in the early stages of stroke." (PMID 32489699, 2020).
Cerebral ischemia (1 paper, 2016). Restriction of arterial blood supply to the brain associated with insufficient oxygenation to support the metabolic requirements of the tissue. "Finally, we show that sustained activation of glutamate receptors, a condition occurring in brain ischemia that down-regulates GABAB receptors, considerably increased the expression of MIB2 and Lys-63-linked ubiquitination of GABAB receptors." (PMID 27573246, 2016).
Cowden syndrome (1 paper, 2018). "Further studies are required to determine the implication of CEACAM1 and MIB2 in the severity of Cowden syndrome in our proband and occurrence of early onset MALT lymphoma in a parent." (PMID 30233642, 2018).
endometriosis (1 paper, 2021). The growth of functional endometrial tissue in anatomic sites outside the uterine body. "MIB2 is differentially expressed in various endometriotic lesions and regulates the endometriosis-associated Notch signaling pathway and the NF-kB cascade." (PMID 34445738, 2021). "Thus, it may lead to the release of more MIB2 from the endometrial stromal cells to the receipt cells in the uterine or the abdominal cavity and to an additional contribution to the pathogenesis of endometriosis." (PMID 34445738, 2021).
gastropathy (1 paper, 2025). "One example of a potential new gene–phenotype relationship is the identification that MIB2 variants are possibly associated with a gastropathy that resembles Ménétrier disease." (PMID 39982357, 2025).
inflammatory skin disease (1 paper, 2024). Inflammatory skin disorders covers a broad category that includes many conditions ranging in severity, from mild itching to grave medical health complications These disorders are common in people of all ages and races. "This discovery advances our comprehension of inflammatory cytokines and chemokines associated with cpdm pathogenesis and highlights the significance of MIB2 in inflammatory skin disease that is independent of its ability to regulate TNF-induced cell death." (PMID 38156288, 2024).
Insulin resistance (1 paper, 2021). Increased resistance towards insulin, that is, diminished effectiveness of insulin in reducing blood glucose levels. "Additionally, mindbomb E3 ubiquitin protein ligase 2 (MIB2), anaphase promoting complex subunit 1 (ANAPC1), and ELOC, Elongin C (TCEB1), are also involved in ubiquitination, which can affect the development of insulin resistance and MetS." (PMID 34516309, 2021).
ischemia (1 paper, 2020). A hypoperfusion of the BLOOD through an organ or tissue caused by a PATHOLOGIC CONSTRICTION or obstruction of its BLOOD VESSELS, or an absence of BLOOD CIRCULATION. "Taken together, our results reveal a critical role of Mib2 in microglial activation and ischemia-induced brain injury, thus providing a potential target for the treatment of stroke." (PMID 32489699, 2020). "Taken together, our results show that microglial deletion of Mib2 mitigates ischemia-induced neuroinflammation and stroke-induced brain injury." (PMID 32489699, 2020). "We are the first to report that microglial Mib2 knockout significantly alleviates ischemia-induced brain injury, suggesting that microglial Mib2 has a detrimental role in this process." (PMID 32489699, 2020). "Furthermore, we generated a microglia-specific Mib2 knockout mice and found that microglia-specific deletion of Mib2 significantly alleviates ischemia-induced neuroinflammation and brain injury." (PMID 32489699, 2020).
ischemic stroke (1 paper, 2020). A stroke disorder caused by obstruction of blood flow to the brain, due to thrombotic (local blood clot formation) or embolic (due to a blood clot or other material traveling from another site) event. "Furthermore, microglial deletion of Mib2 reduces the microglial activation, neuroinflammation, and brain damage after ischemic stroke, suggesting that Mib2 might be a potential therapeutic target in stroke treatment." (PMID 32489699, 2020). "Furthermore, microglia specific deletion of Mib2 reduces its activation and neuroinflammation as well as brain damage after ischemic stroke, implicating that Mib2 might be a potential therapeutic target in stroke treatment." (PMID 32489699, 2020).
lung adenocarcinoma (1 paper, 2023). A carcinoma that arises from the lung and is characterized by the presence of malignant glandular epithelial cells. "Through mining the public TCGA dataset, we detected that MIB2 is significantly up regulated in both lung adenocarcinoma and lung squamous carcinoma tumor tissue." (PMID 37436668, 2023).
neuroblastoma (1 paper, 2015). Neuroblastoma (NB) is the most common solid, extracranial childhood tumor. "Mib2, which is also known as skeletrophin, is a RING finger ubiquitin ligase that was originally cloned from aggregated neuroblastoma cells and shown to interact with alpha-actin." (PMID 26519518, 2015).
non-small cell lung carcinoma (1 paper, 2023). A group of at least three distinct histological types of lung cancer, including non-small cell squamous cell carcinoma, adenocarcinoma, and large cell carcinoma. "MIB2 may be an important clinical marker and may serve for precise targeted therapy in non-small cell lung cancer." (PMID 37436668, 2023).
Obesity (1 paper, 2025). Accumulation of substantial excess body fat. "In terms of metabolisms, Mib2 promoted PTEN proteasomal degradation to inhibit FoxO1‐dependent Ucp1 (Uncoupling protein‐1) transcription in brown adipose tissue, which triggers obesity." (PMID 40159625, 2025).
psoriasis (1 paper, 2024). An autoimmune condition characterized by red, well-delineated plaques with silvery scales that are usually on the extensor surfaces and scalp. "It is unlikely that MIB2 limits dermatitis by suppressing IL-12 signaling, as the administration of IL-12 resolves the dermatitis of Sharpincpdm mice up to 3 weeks post administration, and some clinical evidence suggests a protective role for IL-12 in psoriasis patients." (PMID 38156288, 2024).
rhabdomyosarcoma (1 paper, 2018). A rare aggressive malignant mesenchymal neoplasm arising from skeletal muscle. "Some cells, such as the rhabdomyosarcoma cell line Kym1, were exclusively reliant on MIB2, as mere knockdown of MIB2, using two independent small interfering RNA (siRNA) oligos, induced cell death and loss of clonogenic growth potential." (PMID 29642005, 2018).